VCX (variable charge X-linked)
Description:
May mediate a process in spermatogenesis or may play a role in sex ratio distortion.
Synonyms: VCX-10r; VCX-B1; VCX1; VCX10R; VCXB1
Tractability: No criterion of Open Targets' tractability assessment is met for any kind of drug.
Gene: Protein-coding gene on chromosome X (7,842,262 to 7,844,143, forward strand). Ensembl gene ENSG00000182583.
Gene Ontology:
Molecular function: chromatin binding
Biological process: brain development; chromatin organization; ribosome assembly; spermatogenesis
Cellular component: nucleolus; nucleus
Homologues: Paralogues in human: VCX3B (94% identical), VCX3A (89% identical), VCX2 (60% identical), VCY (53% identical), VCY1B (53% identical).
Diseases named in the same sentence as VCX in open-access papers:
VCX is named in the same sentence as 18 diseases in open-access papers, as found by Europe PMC text mining. Sharing a sentence is not in itself a finding about the gene and the disease. The quoted sentences say what the papers report.
Cognitive impairment (2 papers, 2014 to 2020). Abnormal cognition is characterized by deficits in thinking, reasoning, or remembering. "VCX genes role in cognitive impairment has been demonstrated; in addition these genes might contribute to the onset of neuropsychiatric illness, i.e. attention deficit hyperactivity disorder." (PMID 25182979, 2014).
Intellectual disability (2 papers, 2020 to 2023). "Patient 2 of Esplin and three CNV patients from Decipher (DCP280938, DCP250671, and DCP251340) involving HDHD1, STS, VCX, PNPLA4 also display intellectual disability." (PMID 31963867, 2020). "Studies have shown that the absence of the VCX gene could contribute to an intellectual disability phenotype." (PMID 37013593, 2023).
non-small cell lung carcinoma (2 papers, 2016 to 2020). A group of at least three distinct histological types of lung cancer, including non-small cell squamous cell carcinoma, adenocarcinoma, and large cell carcinoma. "It has been demonstrated that VCX was overexpressed in a subset of non-small cell lung cancer (NSCLC) cell lines and tumor tissues, suggesting that it has oncogenic role." (PMID 27705943, 2016). "Members of the VCX/Y family have recently been found to be potential immunotherapeutic targets for non-small cell lung cancer (NSCLC) and antibodies directed against the VCX protein were found in these patients, indicating that VCX is immunogenic." (PMID 33634013, 2020).
breast carcinoma (1 paper, 2020). "We found that the expression level of VCX2 and other VCX genes correlate with promoter methylation in breast cancer and melanoma, suggesting that these genes can be induced by DNA methyltransferase inhibitors." (PMID 33634013, 2020). "RNA sequencing analysis also indicated that VCX2 might be less frequently expressed in melanoma and breast cancer than other VCX gene family members (VCX and VCX3A)." (PMID 33634013, 2020). "With the potential of clarifying if the VCX/Y family genes could be induced by demethylation, we investigated if the expression of VCX2 and other VCX genes were correlated with promoter methylation in breast cancer and melanoma." (PMID 33634013, 2020).
Syngnathia (1 paper, 2025). "Syngnathia has been associated with neural crest dysregulation, but the absence of STS or VCX in such pathways implies a multifactorial etiology." (PMID 40882285, 2025).
triple-negative breast carcinoma (1 paper, 2020). An invasive breast carcinoma which is negative for expression of estrogen receptor (ER), progesterone receptor (PR), and human epidermal growth factor receptor 2 (HER2). "First, we investigated the expression of VCX genes in MDA-MB-231 triple-negative breast cancer cells after treatment with either vehicle or guadecitabine using RNA sequencing." (PMID 33634013, 2020).
X-linked ichthyosis (1 paper, 2017). "VCX encodes a small, highly charged protein of unknown function and has been previously studied for its involvement in PRDM9-related non-homologous recombination events and X-linked ichthyosis." (PMID 29072575, 2017).
cancer (2 papers, 2016 to 2020). A tumor composed of atypical neoplastic, often pleomorphic cells that invade other tissues. "In this study, we characterized the expression of VCX2, a member of the VCX/Y cancer/testis antigen family, in a large panel of normal tissues and tumors from multiple cancer types using immunohistochemical staining and RNA expression data." (PMID 33634013, 2020). "We further compared the expression of VCX2 to that of other VCX/Y gene members among normal and cancer tissues." (PMID 33634013, 2020). "As one member of novel cancer/testis (CT) antigen, VCX exclusively expresses in testis and is most likely restricted to male germ cells, moreover, its expression is regulated epigenetically." (PMID 27705943, 2016). "We aimed to further investigate the potential of VCX/Y as new targets for immunotherapy, focusing mainly on VCX2, by investigating VCX2 expression in normal and cancer tissues and examining the inducibility of VCX2 by epigenetic treatment." (PMID 33634013, 2020). "In this study, we have demonstrated that VCX2 and other VCX genes are amenable to epigenetic induction by DNA methyltransferase and HDAC inhibitors in cancer cell lines and tumors and therefore may represent new targets for cancer immunotherapy." (PMID 33634013, 2020).
tumor (2 papers, 2016 to 2017). "We found that the L104P mutation in the VCX gene (Variable charge, X-linked) was detected with increasing frequencies from normal, to adjacent tissues and then to tumor tissues; with frequencies of 14.6% in HCC, 11.1% in adjacent tissues, and absent (0%) in white blood cell samples." (PMID 28412734, 2017). "Increasing frequency of the mutation in the VCX gene from zero percent in the blood samples, to 11.1% in the adjacent tissues and then to 14.6% in the tumor tissues suggesting that this mutation might be a tumor driver gene driving HCC carcinogenesis." (PMID 28412734, 2017).
inborn disorders (1 paper, 2023). "In fact, members of the VCX gene family are also ubiquitously expressed across multiple adult tissues, albeit at much lower levels, and are known to be involved in inborn disorders." (PMID 37208698, 2023).
VCX also shares sentences with these, for which no sentence is quoted: attention deficit-hyperactivity disorder (1 paper); autism (1); autism spectrum disorder (1); developmental delay (1); focal epilepsy (1); hepatocellular carcinoma (1); ichthyosis (1); melanoma (1).